IL6 (interleukin 6)
Diseases named in the same sentence as IL6 in open-access papers (continued):
Sharing a sentence is not in itself a finding about the gene and the disease.
tumor (continued). "The presence of TGF-β and other pro-inflammatory cytokines, such as tumor necrosis factor-alpha (TNF-α), interleukin-6 (IL-6), and IL-8, induce the expression of proteins associated with tumor promotion." (PMID 34178680, 2021). "Previous study showed that IL-6 is markedly associated with aggressive tumor behavior and poor outcomes in ESCC." (PMID 34393797, 2021). "So far, studies point towards a pro-tumorigenic role for most of the obesity-associated cytokines, whereof some, i.e., TNF-α, IL-6, and IL-10, also seem to induce activities inhibiting tumor progression." (PMID 34944905, 2021). "On the other hand, IL-6 also presenst a fairer face that is associated with anti-tumour adaptive immunity." (PMID 33923108, 2021). "Anti-IL-6 targeting is a promising therapeutic approach in many ways, since activation of IL-6 signaling is associated, for instance, with aggressive tumor growth, metastasizing and poor responsiveness to chemo- and radiotherapy." (PMID 34681685, 2021). "There is evidence that decreased muscle mass causes reduced expression and the liberation of IL-6 and IL-15, which play a significant role in the redistribution and infiltration of natural killer cells involved in tumor cells elimination." (PMID 34684550, 2021). "In our study, CT26 tumor-bearing mice exhibited weight loss and significantly elevated serum IL-6 and IL-1 levels." (PMID 34724970, 2021). "The presence of so many monocytes in the tumor is thought to be the result of macrophage chemotaxis caused by the expression of many cytokines, such as IL6, IL-11, IL-7, PTHrP, and TGFβ from neoplastic stromal cells." (PMID 34257573, 2021). "Various kinds of gene mutation are the radical reason of tumor generation and IL-6/JAK/STAT3 aggravate the influence by promoting excessive gene expression." (PMID 33390844, 2021). "Regarding the present IL-6 content of the various tumor-associated cells, the following were determined: intra-tumor lymphocytes: 4/28, interphase zone lymphocytes: 0/28, tumor cells 9/28 and most density was seen in vascular cells: IL6 24/28." (PMID 32621022, 2021). "Patients with high proportion of CD45+Rab37+IL-6+ cells per region of interest (ROI) were significantly associated with advanced tumor stage (stages III and IV; P < 0.01)." (PMID 34093869, 2021). "In detail, increased IL-6 levels were associated with increased tumor size and the presence of nodal metastasis in OSCC patients." (PMID 34681685, 2021). "Increased expression of IL-6 systemically and within the tumor microenvironment is attributed both to cancer cells and tumor-associated stromal cells." (PMID 33651821, 2021). "In the current study, IL-6 signaling blockade reduced the anti-angiogenic activity and associated anti-tumor activity of Bev in vitro co-culture system of OCCC cells and HUVECs." (PMID 33833265, 2021). "An up-regulation of IL-6 in the CSF has been reported and associated with tumor infiltrating macrophages." (PMID 34654395, 2021). "A high concentration of serum IL-6 has been shown to be associated with aggressive tumour types and poor disease-free and overall survival." (PMID 33806019, 2021). "IL-6 regulates many gene products that cause tumor cell growth, evasion of apoptosis, angiogenesis, metastasis, and immunomodulation of the TME." (PMID 34178680, 2021). "Several studies suggest that high levels of tumor-associated macrophages (TAMs), interleukin-8 (IL-8), and IL-6 in the TIME are related to the poor therapeutic effect of anti-angiogenic drugs." (PMID 33746989, 2021). "In summary, our results suggest that the TME in the OS xenograft is acidic and that intratumoural acidosis induced the release of IL6 by tumour-associated MSC." (PMID 34831016, 2021). "These complex mechanisms can be associated with a variety of cytokines, such as IL‐6 and Sox2, which give diffuse GC a unique tumor immune environment." (PMID 33410261, 2021).
tumor (continued). "An association of Arid5a-regulated molecules, such as IL6, Tbet, Stat3, Ox40, and Pparγ, has been widely studied in various cancers and tumor models." (PMID 35126382, 2021). "Other studies have shown that besides cancer cells, tumor-associated macrophages (TAMs) and cancer-associated fibroblasts (CAFs) also produce and release IL-6." (PMID 34441316, 2021). "As in the case of IL-6 and IL-8, this proinflammatory molecule is implicated in the growth, proliferation, and immune escape of tumor cells." (PMID 34830096, 2021). "Meriva administration after cryoablation stimulates CD8+ T cells to multiple tumor-associated antigens such as Mage-b and survivin (both expressed in 4T1 tumors), probably through the reduction in IL-6 in the TME." (PMID 34948368, 2021). "In summary, our results show that IL6 is associated with deterioration in liver function independently from tumor progression, as well as progression-free survival." (PMID 34080071, 2021). "Not only cancer cells themselves are considered primary sources of IL-6, but also tumor-associated macrophages (TAMs), MDSCs, and cancer-associated fibroblasts (CAFs)." (PMID 34671021, 2021). "Given above, our results indicate that TCs have a unique tumor-related molecular background, which is characterized by IL6&TNF associated immune suppression." (PMID 34862879, 2021). "In iKras*; IL-6-/- model, we observed deficiency of IL-6 resulted in reduction of tumor infiltrating macrophages and MDSCs." (PMID 34290984, 2021). "In RCC serum IL-6 levels have been associated with extended tumor stage, grade and metastatic progression." (PMID 32621022, 2021). "EphA2 loss of function in tumor cells impaired osteoclast progenitor differentiation in coculture, which is mediated, at least in part, by reduced expression of IL‐6." (PMID 33869989, 2021). "IL-10, alone or in concert with IL-6, causes the upregulation of macrophage B7-H4 expression, which is responsible for the suppression of tumor-associated antigen-specific T cell immunity." (PMID 33418996, 2021). "Tumour and tumour-associated cells produce and secrete various immunosuppressive factors to inhibit NK cell activation, including interleukin (IL)-6, IL-10, transforming growth factor-β (TGF-β), and prostaglandin E2 (PGE2)." (PMID 34306099, 2021). "IL6 IHC staining showed that the expression of IL6 in both two types of tumor samples from high-risk patients was significantly higher than those of the corresponding low and intermediate risk populations." (PMID 34790130, 2021). "In HCC, the activated NF-κB pathway enhances GM-CSF and IL-6 secretion by tumor and tumor-associated endothelial cells, respectively, which facilitate MDSC recruitment." (PMID 33406733, 2021). "We observed a 2.5‐fold decrease in IL‐6 protein levels in 4T1.ΔC‐conditioned medium versus control (p < 0.05), confirming reduced expression in EphA2 loss of function tumor cells." (PMID 33869989, 2021). "The in vivo significance of IL-6 modulating DC function was then shown in a further study investigating the immune status of CT26 tumor-bearing mice that are deficient for IL-6." (PMID 34671021, 2021). "(2019) showed that IL‐6 secretion induced by platinum treatment causes enrichment of CSCs in the residual tumours of high‐grade serous carcinoma (HGSC)." (PMID 34137158, 2021). "CAFs have been shown to regulate T cells through secretion of IL-6 suggesting the higher epithelial Cav-1 expression (and less stromal loss) reflects a tumor microenvironment with fewer CAFs and better immune response." (PMID 34813586, 2021). "In a mouse model, exercise with associated IL6-mediated NK-cell recruitment is associated with reduced tumour growth." (PMID 34572916, 2021).
tumor (continued). "These transplanted tumor cells developed with similar efficiency in both IL-6-proficient and IL-6-deficient syngeneic recipient mice." (PMID 33651821, 2021). "In another study, high serum levels of IL-6 were associated with the tumor stage, tumor size, tumor metastasis, and survival of patients." (PMID 34572955, 2021). "The TNF-alpha has also been reported to be one of the master regulators of tumor-associated inflammation along with IL-6." (PMID 34200663, 2021). "In breast cancer, the specific subgroup of CD10+ and GPR77+ CAF can maintain the stemness of tumor cells by secreting IL6 and IL8 and causing chemotherapy resistance." (PMID 34218518, 2021). "During carcinogenesis, CAFs can produce inflammatory mediators such as CXCL8 and interleukin-6 (IL-6), both of which are associated with inflammation, tumor growth, and angiogenesis." (PMID 34638560, 2021). "MSA (3 mg/kg body weight) inhibited tumor growth by up to 61% compared with the control group, which was associated with a decrease in the levels of tumor necrosis factor TNFα and interleukin 6 (IL6)." (PMID 34205571, 2021). "We studied eight avatar lines, only three of which showed high IL-6; moreover, we are currently unable to associate expression of IL-6 in tumor cells to cachexia-related outcomes in patients with PDAC." (PMID 33851955, 2021). "Il-6 is a key inducer of compensatory regeneration after carcinogen damage, when mutations can become fixed in the DNA and lead to tumor formation." (PMID 34068249, 2021). "M2ds, which are activated by IL-6 and adenosine, are associated with tumor microenvironment and, hence, are named tumor-associated macrophages (TAMs)." (PMID 32625201, 2020). "Several cytokines regulate the NF-κB pathway, and NF-κB also controls the expression of various cytokines, particularly IL-6 and IL-8, which are strongly associated with tumor progression and CSC survival." (PMID 32033472, 2020). "The use of STAT3 inhibitors in prostate cancer limited tumor-associated MDSCs and inhibited interleukin-1β (IL-1β), IL-10 and IL-6 synthesis by monocyte cultures." (PMID 32488850, 2020). "In our analysis, the high correlation between the immune-related gene signature-based risk score and the IL-6/JAK/Stat3 pathway highlighted the tumour-promoting effect of the IL-6/JAK/Stat3 pathway in early-stage LUAD." (PMID 32333046, 2020). "TNF-α, IL-6 and IL-17 have known roles in tumor growth and promotion; IL-6 and IL-10 are produced by tumor-associated macrophages and create conditions of immune suppression and angiogenesis; IL-1β and IL-6 promote angiogenesis and tumor invasion." (PMID 33396710, 2020). "The receptor of IL-17 present on tumor and tumor-associated stromal cells can induce the IL-6 production when activated leading to activation of the oncogenic factor STAT3." (PMID 32121394, 2020). "Paradoxally, lower concentrations on intra tumoral IL-6 showed a positive anti-tumour effect in association with VEGF reduction resulting in less tumour volume in groups that did exercise before and after malignancy." (PMID 33371214, 2020). "There are three kinds of lncRNAs are identified in MDSCs; that is, lnc-C/EBPβ, lncRNA-RNCR3 and lnc-chop, which are significantly elevated in response to tumor-associated and extracellular inflammatory factors such as IL6." (PMID 33148302, 2020). "The cytokine IL-6 has been implicated in regulation of tumor cell proliferation and survival, migration, invasion, angiogenesis, and chemotherapy resistance." (PMID 32528731, 2020). "Aligning the expression of a M1 marker such as TNFα or a M2 marker such as IL-6 with functional activity will help determine the signaling consequences in tumor associated macrophages." (PMID 32318332, 2020). "CRC‐derived sEVs‐miR‐21 is capable of polarizing liver macrophages into an IL‐6‐secreting phenotype by binding to TLR7 in tumor‐associated macrophages (TAMs), which contributes to the creation of an inflammatory PMN." (PMID 33377655, 2020).
tumor (continued). "Both IL-6 and IL-8 are associated with a cascade of invasion, metastasis, and tumor cell inflammation." (PMID 32733941, 2020). "In accordance with our in vitro findings, inhibition of ActRII caused a significant reduction of cancer‐derived human IL‐6 in serum from the tumour‐bearing mice." (PMID 31436048, 2020). "In the tumor microenvironment, IL-6 is mainly secreted by TAMs and is associated with tumor progression and invasion." (PMID 32326073, 2020). "Several pro-inflammatory cytokines, including IL-6 and TNFα, have been linked to the wasting phenotype in tumor-bearing hosts." (PMID 33014286, 2020). "In this case, inhibition of Notch3 has given rise to elevated tumor growth and to increased IL-6 expression by the tumor cells, which then caused CSC expansion." (PMID 32605277, 2020). "The pro‐inflammatory cytokines IL‐4 and IL‐6, produced either by host immune cells or by tumor cells themselves, are associated with tumor malignancy in patients and animal cancer models." (PMID 32485045, 2020). "These T-EVs have been revealed to trigger DCs and cause IL-6 secretion, which enhances tumour invasion by increasing MMP-9 metalloproteinase expression." (PMID 33081785, 2020). "Particularly, autophagy-dependent secretion of IL-6 has been implicated in tumor cachexia and the metastatic potential of Ras-transformed cancer cells." (PMID 33365273, 2020). "F. nucleatum can induce expression of the pro-inflammatory cytokines in epithelial cells, including IL-6 and IL-8, which can contribute to the dynamic cross-talk between tumor cells and cancer-associated fibroblasts (CAF) in the TME for ESCC." (PMID 32676460, 2020). "Multiple tumor cytokines correlated with mortality, most strongly interleukin-6 (IL-6); high IL-6 expression was associated with significantly decreased survival." (PMID 32560494, 2020). "With these findings in mind, it is interesting to note that another pro-inflammatory cytokine, IL-6 has been highly implicated in tumor-promoting processes and in Notch-related pathways in BC." (PMID 32605277, 2020). "IL-6 overexpression has been associated with tumor progression, inhibition of cancer cell apoptosis, stimulation of angiogenesis, and drug resistance." (PMID 32397183, 2020). "IL-6 from TAMs promote an inflammatory environment associated with the prolongation of CSC-like features of tumor cells in the premalignant stage, primary tumors, and metastatic stage." (PMID 32726950, 2020). "It has been reported that HER2-induced secretion of IL-6 can act in an autocrine fashion in human tumor cells causes STAT3-mediated gene expression and signaling activation and facilitates oncogenic growth." (PMID 32683421, 2020). "The deregulated overexpression of IL6 is associated with tumor progression through inhibition of cancer cell apoptosis, stimulation of angiogenesis and drug resistance." (PMID 32308549, 2020). "In cancer, MDSCs induced the upregulation of IL-10 that downregulates macrophage IL-6 and IL-12 and tumor necrosis factor (TNFα) production, thereby polarizing tumor-associated macrophages (TAMs) toward a tumor-promoting M2 phenotype." (PMID 32983164, 2020). "IL-6, which is secreted by tumor-associated stroma has been shown to play an important role in the enrichment of OC stem cells after treatment with platinum agents." (PMID 32257947, 2020). "IL-6 expression has been implicated as one of the main cytokines involved in creating a favorable niche, via bone remodeling, for re-establishment of tumor cells into the metastatic site." (PMID 32585812, 2020). "Gastrocnemius IL-6 was also positively associated with different markers of tumour oxidative response (total and reduced glutathione, enzymatic activity of glutathione reductase, COXs total and COX-1)." (PMID 32472095, 2020).
tumor (continued). "Other factors include proinflammatory cytokine production in tumor microenvironment (e.g., IL-6), tumor-associated viruses (e.g., HPV, HCV), prolonged hypoxia and stress hormones, and/or other hormones (testosterone, E2, dexa)." (PMID 32977489, 2020). "In the TME, tumor-associated fibroblasts (TAFs), macrophages (TAMs) and mesenchymal stem cells secrete interleukin 6 (IL-6), interleukin 8 (IL-8), and chemokine (C-X-C motif) ligand 7 (CXCL7), stimulating the self-renewal of CSCs." (PMID 33014829, 2020). "Tumor cells secrete IL-6, which interacts with the IL-6 receptor (IL-6R) on tumor-associated LECs in TME or on LECs in distant organs." (PMID 32630699, 2020). "A TLR9/IL-6/JAK/STAT3 pathway in tumor-associated myeloid cells plays an essential role in initiating the cancer recurrence after radiotherapy." (PMID 32788720, 2020). "Various interleukins expressed by TAMs are also associated with tumor progression and prognosis, including IL-6, IL-10, CCL5, and CXCL8." (PMID 32268527, 2020). "It has been reported previously that infection of endothelial cells by KSHV induces the expression of cytokines including IL-6, IL-10, IL-13, and angiopoietin-2 that drive monocytes to differentiate and polarize into tumor-associated macrophages (TAMs)." (PMID 33294468, 2020). "Sustained activation of JAK/STAT signaling is frequently linked to cancer cell proliferation, survival, metastasis, tumor immunosuppression, and angiogenesis, and IL-6-mediated apoptosis inhibitory." (PMID 32293402, 2020). "This tumour-promoting effect was associated with HCK capacity to induce tumour-promoting M2-like macrophages and the accumulation of IL-6/lL-11 family cytokines." (PMID 32717909, 2020). "The specific role of ADAM17 in CRC, however, appears to be multifaceted as all three major ADAM17-regulated pathways (TNFα-, EGF-R- and IL-6-signaling) on different cell types are implicated in tumor progression." (PMID 33143292, 2020). "For example, IL-4 synergizes with IL-6 and IL-10 to promote cathepsin secretion in tumor-associated macrophages via UPR activation, resulting in cancer cell invasion." (PMID 32085512, 2020). "CRP levels have been reported to reflect the microenvironment and aggressiveness, such as tumor angiogenesis, in association with IL6." (PMID 32824226, 2020). "On the other hand, previous studies have described that IL-10 deficiency leads to elevated levels of TNF-alpha, IL-6, and IL-17, triggering chronic inflammation and promoting tumor growth." (PMID 32947866, 2020). "Acute inflammation was associated with IL-6 release and massive infiltration of granulocytic myeloid cells (CD11b+Ly6G+) to the tumor bed as well as to the TDLNs." (PMID 32107566, 2020). "It was proposed that IL-6, released by adipocytes in pro-inflammatory condition, promotes WNT5a expression in PC cell and this in turn mediates phenotypic remodeling of tumor-associated adipocytes." (PMID 32659999, 2020). "CAFs produced IL-6 and GM-CSF, which together induced the infiltration of tumor-associated macrophages (TAMs) and their differentiation into M2-like phenotypes in mouse syngeneic colon carcinoma models, thereby suppressing tumor immunity." (PMID 33050237, 2020). "IL6 is also plays a role in the generation of tumor-associated macrophages by skewing monocyte differentiation into tumor-associated macrophage." (PMID 32455670, 2020). "Circulating IL-6 levels are linked to tumour necrosis and both local and systemic inflammatory responses in patients undergoing resection for colorectal cancer." (PMID 33257741, 2020). "This resulted in increased production of IL-6 by IL-17 receptor-expressing tumor and tumor-associated stromal cells and concomitantly increased STAT3 signaling and production of pro-survival Bcl-2 and Bcl-xL in melanoma cells." (PMID 32517051, 2020).